CH25H (cholesterol 25-hydroxylase)
Description:
Catalyzes the formation of 25-hydroxycholesterol from cholesterol, leading to repress cholesterol biosynthetic enzymes. Plays a key role in cell positioning and movement in lymphoid tissues: 25-hydroxycholesterol is an intermediate in biosynthesis of 7-alpha,25-dihydroxycholesterol (7-alpha,25-OHC), an oxysterol that acts as a ligand for the G protein-coupled receptor GPR183/EBI2, a chemotactic receptor for a number of lymphoid cells (By similarity). May play an important role in regulating lipid metabolism by synthesizing a corepressor that blocks sterol regulatory element binding protein (SREBP) processing. As an interferon-stimulated gene, has broad antiviral activities against a wide range of enveloped viruses, such as vesicular stomatitis virus (VSV) and SARS coronavirus-2 (SARS-CoV-2). Its product, 25-hydroxycholesterol, activates the ER-localized enzyme ACAT to induce internalization of accessible cholesterol on the plasma membrane and restricts SARS-CoV-2 S protein-mediated fusion which inhibits virus replication. In testis, production of 25-hydroxycholesterol by macrophages plays a role in Leydig cell differentiation (By similarity). Required to restrain inflammation in macrophages: production of 25-hydroxycholesterol protects macrophages from cholesterol overload, thereby preventing mitochondrial DNA release and subsequent activation of the AIM2 inflammasome (By similarity).
Synonyms: C25H
Tractability: Antibody: UniProt predicts a signal peptide or a membrane-spanning region.
Gene: Protein-coding gene on chromosome 10 (89,205,629 to 89,207,317, reverse strand). Ensembl gene ENSG00000138135.
Subcellular location: Endoplasmic reticulum membrane
Pathways (Reactome):
Metabolism: Synthesis of bile acids and bile salts
Gene Ontology:
Molecular function: cholesterol 25-hydroxylase activity; protein binding; steroid hydroxylase activity; iron ion binding
Biological process: cholesterol metabolic process; negative regulation of fusion of virus membrane with host plasma membrane; response to type I interferon; B cell chemotaxis; lipid metabolic process; zymosterol biosynthetic process; lipid biosynthetic process; negative regulation of cholesterol metabolic process
Cellular component: cytosol; endoplasmic reticulum membrane
Genetic constraint (gnomAD): Loss-of-function variants: 11 observed, 17.69 expected, observed/expected ratio (o/e) 0.62, 90% interval 0.39 to 1.03. The upper end of that interval is the gene's LOEUF score, 1.03, which puts it in group 4 of 6, group 1 being the genes least tolerant of losing a copy. Missense variants: 326 observed, 359.14 expected, observed/expected ratio (o/e) 0.91, 90% interval 0.83 to 1. Synonymous variants: 178 observed, 167.11 expected, observed/expected ratio (o/e) 1.07, 90% interval 0.94 to 1.21.
Homologues: Orthologues: chimpanzee CH25H (99% identical), macaque CH25H (95% identical), rabbit CH25H (83% identical), pig CH25H (82% identical), rat Ch25h (80% identical), guinea pig CH25H (79% identical), mouse Ch25h (78% identical), zebrafish ch25h (53% identical), tropical clawed frog ch25h (50% identical), Caenorhabditis elegans F35C8.5 (29% identical). Paralogues in human: MSMO1 (27% identical), FAXDC2 (19% identical), SC5D (19% identical).
Diseases named in the same sentence as CH25H in open-access papers:
CH25H is named in the same sentence as 90 diseases in open-access papers, as found by Europe PMC text mining. Sharing a sentence is not in itself a finding about the gene and the disease. The quoted sentences say what the papers report.
viral infection (37 papers, 2013 to 2026). "Virus infection selectively upregulates the expression of gene encoding cholesterol 25-hydroxylase (CH25H), which is critical for modulation of both AD susceptibility and Aβ production." (PMID 30823925, 2019). "Viral infection induced IFNs up-regulate ISGs (for example, cholesterol-25-hydroxylase) and cause down-regulation of sterol biosynthesis to protect the cells." (PMID 30064395, 2018). "In addition, Kaposi’s sarcoma-associated herpesvirus (HHV8) reduced the expression of CH25H by encoding multiple miRNAs, thus promoting viral infection." (PMID 32640529, 2020). "For ZIKV and WNV, the interferon-induced enzyme cholesterol-25-hydroxylase (CH25H) restricts virus infection through altering lipid composition." (PMID 40517242, 2025). "We detected significant upregulation of CH25H in hCMEC/D3 cells exposed to poly(I:C), a synthetic double-stranded RNA analogue that mimics viral infections, and to IFNβ." (PMID 40406995, 2025). "Here, we demonstrate that HEVs strongly express cholesterol-25-hydroxylase (Ch25h) and upregulate expression acutely during viral infection." (PMID 39708807, 2025). "Under normal conditions, CH25H is expressed at low levels in humancells; however, its expression is significantly upregulated in response tointerferons, particularly during viral infections." (PMID 41117538, 2025). "Here, we show that the oxysterol biosynthetic enzyme cholesterol-25-hydroxylase (Ch25h) is upregulated in LN high endothelial venules during viral infection." (PMID 39708807, 2025). "Viral infection activates antiviral responses in the host cell, including the transcription of interferon-induced genes (ISGs), such as the cholesterol 25-hydroxylase (CH25H) gene, whose product modifies cholesterol into 25-hydrocholesterol (25HC)." (PMID 38106410, 2023). "Several pieces of evidence have suggested the antiviral potential of cholesterol-25-hydroxylase and importance of cholesterol in viral infection." (PMID 36314946, 2022). "Although the expression of CH25H is low and stable in most organs under normal physiological conditions, it is significantly increased by viral infections, Toll-like receptor agonists, and under inflammatory conditions." (PMID 35011433, 2021). "In mammalian cells virus infections lead to the accumulation of the oxysterol 25-hydroxycholesterol (25HC), an antiviral factor, which is produced from cholesterol by the cholesterol 25 hydroxylase (CH25H)." (PMID 33717065, 2021). "In early studies it was shown that in response to viral infection macrophage generated IFN activates the expression of Ch25h with the resultant generation and secretion of 25-HC providing both a paracrine and autocrine antiviral response." (PMID 34690800, 2021). "In normal circumstances, the level of 25‐HC is low in tissues and in the circulation; however, upon bacterial or viral infection CH25H (Ch25h in mouse) is upregulated in activated macrophages with the consequent enhanced formation of 25‐HC." (PMID 33506652, 2021). "Recent evidence showed that the CH25H gene is one of the ISGs, and many viral infections can induce the upregulation of CH25H in most mammal cells." (PMID 32640529, 2020). "Viral infection and TLRs ligands induced CH25H expression by activating the TRIF adaptor and its downstream IFN-β/JAK/STAT signaling pathway." (PMID 32640529, 2020). "For example, CH25H expression is upregulated during viral infections including ZIKV, HIV, VSV, HCV, and murine cytomegalovirus (MCMV), and then a series of antiviral cytokines are induced, such as IFN-γ, TNF-α, and IL-2, to inhibit viral replication." (PMID 32640529, 2020). "Elevated Ch25h expression and 25HC production have been identified as defense mechanisms in macrophages during various viral infections, raising the possibility that systemic infections could exacerbate AD pathology through increased 25HC." (PMID 40001197, 2025). "Viral infections can lead to increased expression of ch25h in salmon." (PMID 39211041, 2024).
viral infection (continued). "Thus, the present study suggested a new mechanism for the role of CH25H in the regulation of viral infection and replication, which provided a detailed understanding of the cross talk between the host and virus." (PMID 35587189, 2022). "Furthermore, in zebrafish (Danio rerio) several paralogues of human cholesterol 25-hydroxylase have been described with the mRNA expression of one paralogue ch25h_b being highly inducible by viral infections." (PMID 33717065, 2021). "To test whether signaling from Ifnar1 was necessary for the induction of Ch25h during viral infection, we next conducted de novo synthesis experiments in Tyk2−/− macrophage cells." (PMID 23273843, 2013). "However, the expression of CH25H varies in response to various viral infections." (PMID 37455710, 2023). "CH25H was proved as a member of the interferon-stimulating genes (ISGs) family, meanwhile, 25HC seems to have similar features to CH25H and is augmented in macrophages after viral infection and by interferon signaling and shows great potential to counteract the enveloped viruses." (PMID 37781400, 2023). "Distinct from the majority of viral infections that induce CH25H upregulation, JEV infection elicits a transient reduction in CH25H abundance immediately after infection, coupled with a persistent elevation in SREBP2 expression." (PMID 42075137, 2026). "This lipid effector synthesis from cholesterol is catalyzed by cholesterol-25-hydroxylase, whose expression is induced by interferon (IFN) in macrophages as an innate response to viral infection." (PMID 37766327, 2023). "Caco-2 cells also exhibit CH25H upregulation upon SARS-CoV-2 infection, and the overexpression of CH25H inhibits SARS-CoV-2, as well as SARS-CoV-2 pseudovirus particle production in Vero cells, indicating an effect at the entry step of viral infection." (PMID 38106410, 2023). "The enzyme cholesterol 25-hydroxylase (CH25H, belonging to the ISGs) is highly induced during SARS-CoV2 infection and restricts viral infection by depleting cholesterol on the plasma membrane." (PMID 35154105, 2022). "CH25H, a hepatic enzyme catalyzing the hydroxylation of cholesterol to 25-hydroxycholesterol(25HC), has been proved to be an antiviral interferon-stimulated gene (ISG), which protected mice from viral infection by producing 25HC to broadly inhibit viral entry." (PMID 39287458, 2024). "In addition, we noted expression of genes mediating anti-viral response (i.e., CH25H and IFITM3), which confers high viral infection resistance to various tissue SCs." (PMID 37652013, 2023). "Upon SARS‐CoV‐2 viral infection, IFN, CH25H and other IFN‐stimulated genes are upregulated." (PMID 33506652, 2021). "Ch25h is an interferon (IFN) regulated gene and upon viral infection, or IFN-stimulation, 25-HC is synthesised by macrophages and acts as a potent paracrine inhibitor of viral infection demonstrating a role in the innate immune pathway." (PMID 29421651, 2018). "Upon viral infection, type I IFNs (α, β, etc.)play a major role in initiating the Janus kinase (JAK)-signal transducer and activator of transcription (STAT) pathway and inducing numerous interferon-stimulated genes (ISGs), including Cholesterol 25-hydroxylase (CH25H)." (PMID 40928246, 2025). "CH25H does not seem to be a classical ISG in human hepatoma cells, as it cannot be induced by type I IFNs, and it represents a direct innate immune response to viral infection." (PMID 37631994, 2023).
atherosclerosis (7 papers, 2018 to 2025). A disease characterized by the build-up of fatty material and calcium deposition in the arterial wall resulting in partial or complete occlusion of the arterial lumen. "Other studies have shown that CH25H is involved in macrophages’ functional endothelium and anti-inflammatory phenotype and that CH25H ablation increases susceptibility to atherosclerosis." (PMID 36863716, 2023). "In addition, Ch25h expression by ECs contributes to atherosclerosis development." (PMID 36715148, 2023). "A similar expression pattern is visible in other inflammation and atherosclerosis related genes such as APOE, KLF4, CXC3L1, STC1, CH25H, and ABCG1." (PMID 39695567, 2024). "KLF4 induces the expression of cholesterol-25-hydroxylase (Ch25h) and liver X receptor (LXR) in ECs, which contribute to reverse cholesterol transport out of the vascular wall and inhibition of endothelial inflammasome activation, both protective against atherosclerosis." (PMID 29459900, 2018).
Alzheimer disease (6 papers, 2007 to 2026). A progressive, neurodegenerative disease characterized by loss of function and death of nerve cells in several areas of the brain leading to loss of cognitive function such as memory and language. "This study investigates the role of 25-hydroxycholesterol (25HC), a metabolite produced by cholesterol hydroxylase encoded by the Ch25h gene, in modulating microglial function and its potential implications in Alzheimer’s disease (AD) pathology." (PMID 40001197, 2025). "Ch25h has also been proposed as a susceptibility gene for Alzheimer’s disease and its deletion can significantly attenuate EAE disease course by limiting trafficking of pathogenic CD4+ T lymphocytes to the central nervous system." (PMID 27355629, 2016). "Serpina3n (a mouse homologue of α1-antichimotrypsin), Cd44, and Ch25h expression levels were also verified, because of the novelty of the gene array results and their possible involvement in the physiopathology of Alzheimer's disease." (PMID 17375196, 2007). "Moreover, CH25H expression was upregulated, and 25-HC promoted IL-1β-mediated neuroinflammation in brain tissue of patients with Alzheimer's disease." (PMID 38716981, 2024). "Cholesterol 25-hydroxylase (CH25H) metabolizes cholesterol to 25-hydroxycholestrol (25HC) and plays a pathological role in osteoarthritis, Alzheimer's Disease, and other diseases." (PMID 42284103, 2026).
colitis (6 papers, 2020 to 2025). Inflammation of the colon. "In inflammatory bowel disease, although exogenous 25-HC shows limited efficacy in murine colitis models, CH25H deficiency alters disease progression, suggesting potential predictive relevance." (PMID 40621094, 2025). "Collectively, these data indicate that Ch25h-deficient mice are highly susceptible to DSS-induced colitis." (PMID 32859970, 2020). "This suggests that CH25H may have a protective role in colitis and is associated with intestinal epithelial regeneration and tissue reconstruction." (PMID 37720208, 2023). "The previous results suggest that Ch25h−/− mice are highly susceptible in experimental colitis and that, we then reasoned that administration of exogenous 25-HC might further attenuate colitic damage." (PMID 32859970, 2020). "To explore the potential role of CH25H in the pathogenesis of DSS-induced colitis model, we generated the Ch25h−/− mice with the CRISPR/Cas9 system." (PMID 32859970, 2020). "Consistent with previous reports, we observed increased expression levels of CH25H in murine DSS colitis tissue." (PMID 32859970, 2020). "Here, this study revealed that CH25H participates in the pathophysiology of colitis in mice through its protective and anti-inflammatory roles." (PMID 32859970, 2020). "In this study, we found that, compared to WT littermates, mice with Ch25h depletion exhibit a higher severity of DSS-induced colitis, including more damage to colonic wall structure and more inflammation." (PMID 32859970, 2020). "Those discrepancies could result from the different disease models used in these studies that investigated Ch25h function in various cell compartments and organs (e.g., colitis, lungs, and CNS inflammation)." (PMID 36715148, 2023). "However, studies have shown that the overexpression of CH25H in ILC-related colitis models can stimulate the pro-inflammatory ILC3 activity and aggravate inflammatory reactions." (PMID 37720208, 2023). "This group also detected increased Gpr183, Ch25h and Cyp7b1 expression in the acute and chronic DSS colitis models, but they did not observe an effect of Gpr183 or Ch25h gene deficiency on inflammation severity." (PMID 36389671, 2022). "Ch25h−/− mice with DSS-induced colitis exhibited aggravated injury, including higher clinical colitis scores, severe injury of the epithelial barrier, lower tight junction protein levels and higher levels of IL-6." (PMID 32859970, 2020). "However, it was reported that the expression of Cyp27a1 was not increased in several colitis models when Ch25h was deleted." (PMID 36389671, 2022).
COVID-19 (6 papers, 2021 to 2023). A disease caused by infection with severe acute respiratory syndrome coronavirus 2. "In addition, a recent study showed that SARS-CoV-2 induces cholesterol 25-hydroxylase (25HC) both in vitro and in COVID-19 infected patients, via interferon signaling." (PMID 34264974, 2021). "For example, except for suppressing ZIKV infection, CH25H as one of the ISGs, was reported to be induced by SARS-CoV-2 infection in vitro and COVID-19-infected patients." (PMID 36209057, 2022). "We demonstrated the downregulation of IFITM10, CH25H, NCR3, and KLRK1 and the upregulation of ID1 in the PBMCs from RTP patients compared with that from patients with moderate or severe COVID-19." (PMID 34687295, 2021). "One of these genes, CH25H, is found to be up-regulated in macrophages and lung epithelial cells found in bronchioalveolar lavage (BAL) fluid from COVID-19 patients." (PMID 34690800, 2021).
influenza (6 papers, 2011 to 2025). An acute viral infection of the respiratory tract, occurring in isolated cases, in epidemics, or in pandemics; it is caused by serologically different strains of viruses (influenzaviruses) designated A, B, and C, has a 3-day incubation period, and usually lasts for 3 to 10 days. "During infection, overexpression of Ch25h increased the susceptibility of mice to Listeria monocytogenes and Mycobacterium tuberculosis and amplified the activation of immune cells and mediators in response to influenza." (PMID 36831236, 2023). "We found that the resistance of H820 cells to influenza infection is likely linked to impaired viral entry—due to high basal levels of interferon-induced proteins known to inhibit endocytosis (IFITM1/2/3, NCOA7, and CH25H)—and to increased expression of mRNAs that encode other antiviral factors." (PMID 40434103, 2025).
melanoma (6 papers, 2020 to 2025). A malignant, usually aggressive tumor composed of atypical, neoplastic melanocytes. "Notably, a recent study showed that low mRNA expression of CH25H in leukocytes of melanoma patients is associated with a poor prognosis." (PMID 36564433, 2022). "Of note, knockdown of CH25H in B16 melanoma cells enhanced the STING signaling, suggesting the causal link between the STING signaling and CH25H/25-HC." (PMID 38212328, 2024). "In a previous study, we demonstrated that cancer cell-derived EVs (TEVs) from melanoma cells and melanoma patients downregulated the type 1 interferon receptor subunit 1 (IFNAR1), resulting in loss of the interferon-stimulated gene (ISG) cholesterol-25 hydroxylase (CH25H)." (PMID 38405101, 2024). "Previous studies have indicated that the expression level of CH25H is an independent prognostic factor for predicting distant metastasis of breast cancer and melanoma, however, its prognostic value in lung cancer remains unclear." (PMID 36564433, 2022). "Additionally, low CH25H levels in leukocytes from melanoma patients were correlated with poor prognosis." (PMID 33381521, 2020). "In animal model, lack of CH25H expression enhances TEV uptake, TEV-induced pre-metastatic niche and melanoma lung metastases." (PMID 33456564, 2021).